BRAF (B-Raf proto-oncogene, serine/threonine kinase)
Diseases named in the same sentence as BRAF in open-access papers (continued):
Sharing a sentence is not in itself a finding about the gene and the disease.
tumor (continued). "The BRAF-mutant tumor samples also contained elevated levels of macrophages, mucosal-associated invariant T cells, cancer-associated fibroblasts, hematopoietic stem cells, common myeloid progenitors, myeloid dendritic cells, and CD4+ T cells compared to the BRAF-wild-type tumor samples." (PMID 39336897, 2024). "Our findings revealed a remarkable association between BRAF expression, hormone receptor negativity, and the non-luminal tumor subtype." (PMID 38919805, 2024). "Mutations in the v-raf murine sarcoma viral oncogene homolog B1 (BRAF) gene, which encodes a serine/threonine protein kinase, also lead to the constitutive activation of RAS-RAF-MEK-ERK cascade, resulting in unchecked cell growth and tumor development." (PMID 39684219, 2024). "Tumor mutation burden (median 4 mutations/Mb) was not significantly different between patients carrying G469V, G469A, V600E, or other BRAF mutations." (PMID 38770647, 2024). "Additionally, we observed a positive correlation between USP4 expression levels and critical clinical parameters, including tumor size, TNM stage, BRAF mutation, decreased recurrence-free survival time, and decreased overall survival time." (PMID 39393052, 2024). "Notably, tumours with RTK/WNT pathway BRAF and RNF43 co-mutations had higher expression of BRAF and lower expression of RNF43 compared with wild-type tumours and tumours carrying mutations of only one gene." (PMID 39112715, 2024). "With its high specificity and sensitivity, and low turnaround time, BRAF VE1 IHC is a great cost-saving first screening tool for this mutation for localized pT4 tumours without any pN or pM disease." (PMID 39661469, 2024). "Thus, inhibitors of SHP2 can block the RTK/RAS/MAPK signaling pathways and inhibit the growth and proliferation of tumor cells driven by RTK or with KRAS, BRAF Class 3 and NF1 loss of function mutations." (PMID 39184861, 2024). "Scholars have speculated that the BRAF gene mutation only participates in the formation of SBOT, but decreases the ability of the tumor to continue to progress." (PMID 38669365, 2024). "Furthermore, other non-BRAF factors such as extrathyroidal tumor invasion, older age, lymph node and distant metastases, and being male have all been tied to poorer prognostic outcomes." (PMID 38539548, 2024). "As both tumour types frequently carry KIAA1549::BRAF fusions, identification of the genetic driver may be insufficient to distinguish the tumour types." (PMID 39294363, 2024). "While generally thought to increase anti-tumor immunity, BRAF inhibitors may also exert competing effects such as driving tumor infiltration by macrophages, which can mediate resistance to BRAF inhibition through TNFα and VEGF." (PMID 38275291, 2024). "For this reason, in the last decade, various pharmacological inhibitors of the MAPK pathway have been used, directed against mutated BRAF (first generation RAF inhibitors as vemurafenib, encorafenib, dabrafenib, sorafenib) or MEK (binimetinib, cobimetinib, trametinib) in tumor therapy." (PMID 39329730, 2024). "Tumor recurrence was more frequent in FGFR1-mutant tumors than in BRAF V600E-mutant tumors." (PMID 39081340, 2024). "In more detail, tumor gDNA from patient 3 had a VAF of 0.5 using a patient-specific fusion assay, indicating a monoallelic BRAF duplication event in a tumor biopsy sample with 100% purity, while the corresponding screening BRAF duplication assay had a CNV = 3.04." (PMID 38371226, 2024).
tumor (continued). "Based on baseline characteristics, patients treated with anti‐PD‐1 monoclonal antibodies in the present cohort had lower tumour burden (expressed as initial serum LDH level and the number of involved organs), and the present study population consisted of exclusively BRAF‐mutated patients." (PMID 38491825, 2024). "Many researchers have therefore used the status of BRAF V600E in tumor lesions to determine whether intraglandular dissemination has occurred." (PMID 39135992, 2024). "In the following years, retrospective analysis of RAS (KRAS, NRAS) and BRAF mutations in tumor tissue samples from patients included in these pivotal trials showed a greater benefit in patients with tumors not harboring RAS/BRAF mutations." (PMID 38711991, 2024). "Additional lines of non-BRAF targeted therapy or Immunotherapy may be assigned if the tumour Genomic Profile exhibits alterations that confer sensitivity to said treatments." (PMID 38184610, 2024). "Seven tumors had BRAF mutation (one was a rare mutation: BRAFp.G469A), six had BRAF fusion, and two were empirically treated; one (#10) had NF1 and one (#14) with DLGNT had small tumor biopsy insufficient for NGS testing." (PMID 39399174, 2024). "A mutational analysis on FFPE tumour tissue and cfDNA extracted from CSF unveiled a unique variant in exon 15 of BRAF, a variant never before identified in this entity." (PMID 39107839, 2024). "Moreover, we report differences in oncogene expression such as MYC, MET and BRAF between ROS1+ tumor samples and cell lines, which should be taken into account when interpreting in vitro experiments." (PMID 39737401, 2024). "Additionally, mutations in BRAF and PIK3CA are observed in some cases, indicating a shift toward a more aggressive tumor profile." (PMID 39768914, 2024). "Median OS and PFS were significantly inferior for patients with CDX2-negative versus CDX2-positive tumours, even after excluding tumours with the BRAF p.V600E allele." (PMID 38439814, 2024). "Extensive tumour genomic heterogeneity was found in CTCs compared to tumour biopsies and cfDNA at failure to BRAF inhibition, in BRAFV600E-mutant NSCLC, including relevant alterations that may represent potential treatment opportunities." (PMID 38177660, 2024). "In this case, CGP identified a BRAF V600E mutation, a targetable tumor-agnostic biomarker, but, to our knowledge, SGT was not ordered to evaluate this specific variant." (PMID 39544293, 2024). "Consistent with the observation that multiple metabolites showed increased levels in BRAF-mutant PTC tumor samples, the controlled IHH4 cells also showed improved levels in a series of metabolites, especially PE and PC species, compared to the BRAF knockdown cells." (PMID 38609408, 2024). "Moreover, identification of certain mutations and molecular markers, such as BRAF V600E, hypermutation or elevated tumor-mutational burden and NTRK fusions allow for the use of FDA approved agents that are tumor-agnostic." (PMID 39361075, 2024). "NGS showed absence of BRAF mutation, a high tumor mutational burden, and an UV-induced DNA damage signature." (PMID 38799429, 2024). "Primary BRAF-mutant tumours show high infiltration of cytotoxic T-cells, even for MSS-CRC." (PMID 38664577, 2024).
tumor (continued). "In addition to targeting BRAF, the integration of therapies that address the tumor microenvironment (TME) presents a promising avenue for enhancing treatment efficacy." (PMID 39336897, 2024). "High RAF (BRAF mutation AF/MaxAF) indicates that these BRAF mutations may drive tumor evolution, so we defined these mutations with RAF > 70% as BRAF‐driven clones." (PMID 38770647, 2024). "Through the elevated levels of CD4+ T cells previously found in BRAF-mutant tumor samples, the BRAF-mutant TME can promote anti-tumor activity through the direct or indirect targeting of tumor cells by CD4+ T cells, which also supports the cytotoxic effects of CD8 + T cells on tumor cells." (PMID 39336897, 2024). "Our data suggest immune-stimulating effects of dabrafenib therapy may be at least partially due to altered MDSC function, a prediction supported by the reduction of PMN-MDSCs in BRAF-mut tumor-bearing mice after dabrafenib treatment." (PMID 38421883, 2024). "In addition, CM samples were stratified according to the main clinical-pathological features, including stage, Breslow thickness, BRAF status, number of mitosis, Tumor-Infiltrating Lymphocytes (TILs), vascular invasion, and ulceration." (PMID 39358721, 2024). "In particular, loss-of-function alterations in the TGFβ pathway genes may occur early in BRAF-driven serrated lesions, contributing to tumor progression through the activation of tumor stroma by TGFβ." (PMID 38731846, 2024). "Subgroup analyses demonstrated mCAPOX/mCAPIRI plus bevacizumab had similar PFS benefits in patients with different ages, sex, performance status, prior treatments, tumor locations or metastases, BRAF mutations, or with conversion therapy or not." (PMID 39658608, 2024). "Tumours with EGFR, ALK, BRAF mutations may be resistant to PD-1/PD-L1 immunotherapy, and are more suitable for targeted therapy or combination therapy." (PMID 39530091, 2024). "However, if there is a heterogenous distribution of BRAF mutated allele in PTC tissue, a late mutation can occur in any part of the tumor, including its periphery." (PMID 38540091, 2024). "Several factors influence survival in CRLM, such as the progression-free interval after surgery for the primary tumor, whether the tumor is metachronous or synchronous, KRAS or BRAF mutation status, CEA levels, and extrahepatic disease." (PMID 39562379, 2024). "They found that higher SUV values were significantly associated with the presence of BRAF V600E mutations, indicating that metabolic activity, as measured by PET/CT, could reflect tumour aggressiveness." (PMID 39598062, 2024). "However, to a certain extent, these inhibitors also act on WT BRAF and other off-targets in tumor cells in a concentration-dependent manner." (PMID 38839106, 2024). "Results showed a BRAF V600E missense mutation (c.1799 T > A, variant allele fraction 13.4%), NFE2L2 missense variant (c.101G > A, variant allele fraction 14.9%), microsatellite stable, and tumor mutational burden 3.7 m/MB." (PMID 38814411, 2024). "For patients without the BRAF mutation, age and advanced tumor stage similarly predict an increased risk of mortality, along with elevated levels of thyroglobulin and calcitonin." (PMID 39767732, 2024). "Genomic testing revealed a KRAS, NRAS, BRAF wild type and a dMMR tumor." (PMID 39064004, 2024). "This study reported promising efficacy against BRAF V600-mutant tumours." (PMID 38333370, 2024).
tumor (continued). "In contrast, multiple BRAF-independent mutations, mainly out of the MAPK pathway were detected in single CTCs by targeted PCR/NGS, while the number of these mutations was much lower in tumour biopsies and cfDNA samples." (PMID 38177660, 2024). "Though there is a co-existence of KRAS mutation and other RAS-effector mutations in the same tumor, KRAS and BRAF mutations do not occur in the same tumor." (PMID 39056802, 2024). "MAPK signaling rebound is recognized as an essential resistance mechanism in BRAF-mutant tumor treatment, so we tested whether a MOGAT3 inhibitor combined with dual therapy would inhibit p-ERK rebound more profoundly than anti-BRAF/EGFR treatment." (PMID 39436710, 2024). "Tumor response was independent of histologic subtype, BRAF alteration type (fusion vs. mutation), number of prior lines of therapy, and prior MAPK-pathway inhibitor use." (PMID 38291372, 2024). "In our case, no mutations in the BRAF gene were detected in the patient’s tumor samples, while CDX2 expression was confirmed, which supports the hypothesis about the correlation between CDX2 expression and the status of the BRAF gene." (PMID 39518386, 2024). "However, they did find a trend for longer mean survival times (MST) for dogs with BRAF p.V595E (n = 16) versus BRAF wildtype tumours (n = 13; 11 months versus 5 months, p = 0.05)." (PMID 38787171, 2024). "Furthermore, we advocate that any subsequent distant metastases that arise in cases where the initial tumour only received BRAF immunohistochemical testing should be re-tested with a larger molecular panel." (PMID 39661469, 2024). "We hypothesize that in CRC, these splicing isoforms and mutant-BRAF may work together to activate signaling pathways that drive rectal and colon carcinogenesis and tumor progression." (PMID 39410512, 2024). "Interestingly, we showed that knocking down Cdx2 significantly reduced the expression of differentiated lineages-related genes such as Muc2, Atoh1, and Guca2a in BRAF mutant tumor-derived organoids." (PMID 38893159, 2024). "Thirty-three patients carried a RAS/BRAF-mutated tumor and were treated with FOLFOX-bevacizumab, and 22 patients had a RAS/BRAF wild-type tumor and were treated with FOLFOX-panitumumab; 18 patients had two or more distant metastases while in the remaining, there was a single metastatic localization." (PMID 39682164, 2024). "Τhe efficacy of this combined treatment is the same in tumours lacking activating mutations in BRAF and in tumours harbouring the most frequent BRAF(V600E) mutation." (PMID 38182748, 2024). "Possible reasons include that the tumor did not have the BRAF mutation, or that the mutated genes were diluted, which reduced the ratio below the detection limit of conventional PCR." (PMID 39272320, 2024). "Long-term follow-up will provide essential insight into the tumour behaviour following treatment cessation and whether BRAF and MEK inhibitor resistance can be explained by novel tumour genetic adaptations." (PMID 39456573, 2024). "Given the paucity of knowledge of mutations in BRAF in feline tumours, it is not used as a molecular biomarker in feline oncology." (PMID 38787171, 2024). "The BRAF peptide vaccination induced potent cytotoxic T cell responses, inhibited tumor growth, and enhanced infiltration of CTLs by remodeling immunosuppressive modules within the tumor microenvironment." (PMID 38355548, 2024). "This metabolic adaptation is generally linked to increased resistance to apoptosis and tumor aggressiveness and it might also be driven by the upregulation of the MAPK signaling pathway in the BRAF-mutant cells, such as the A2058 cell line." (PMID 39695652, 2024).
tumor (continued). "Given the observed association of activating ERBB2 and BRAF mutations with RTK/MAPK pathway transcriptional signature, we hypothesized this association could be related to the PAM50 subtype of these tumor samples." (PMID 38503755, 2024). "Instead, a single dichotomized biomarker where patients with high EREG and high AREG are combined was found to be predictive of panitumumab response rate and survival benefit in KRAS WT patients independent of BRAF mutational status and primary tumor location." (PMID 40727266, 2024). "For example, BRAF allelic imbalance is reported to occur in 40% of BRAF mutant skin cancers." (PMID 38168062, 2024). "One tumor had microsatellite instability and no BRAF mutation or HER2 mutations or amplifications were detected." (PMID 38071748, 2024). "Interestingly, we observed varying organoid sensitivity to panitumumab within the group of left-sided RAS/BRAF-wildtype tumours." (PMID 38414064, 2024). "KRAS mutation has been associated with a poor prognosis in CRC, and so has BRAF mutation, irrespective of MSI status, with BRAF-mutated MSS tumours showing the worst prognosis." (PMID 38040818, 2024). "All tumours that lacked CDX2 expression or had the BRAF p.V600E variant were positive for COX2 expression." (PMID 38439814, 2024). "Although the analysis of clinicodemographic data revealed an association between BRAF mutation status and age and tumor location, these data were not sufficient for predicting CM harboring BRAF mutations." (PMID 39735251, 2024). "In a similar manner, CBLL1 gene expression was associated with non-mutant BRAF samples when analysing 205 samples of CRC patients (20 tumour samples with BRAF mutations and 195 tumour samples with non-mutated BRAF)." (PMID 38339195, 2024). "We detected the BRAF fusion in ctDNA in the CSF sample from the 10-year-old child with the tumor in the 4th ventricle, and since the tumor was located directly in the CSF reservoir, it could be expected to be positive for ctDNA." (PMID 38371226, 2024). "TILs were present in 48.4% of cases and were correlated with lower Clark levels, thin tumor thicknesses, lower mitotic rates, BRAF mutation, absence of neurotropism, lymph node involvement, and disease recurrence." (PMID 39684307, 2024). "Moreover, our results assert that the relationship between tumor metabolism and BRAF inhibition has significant translational implications." (PMID 38254853, 2024). "As expected, varying levels of wild-type BRAF were confirmed to be present in both BRAF-mutated and non-mutated tumours, as shown by ddPCR." (PMID 39591358, 2024). "Finally, we investigated differential expression of P and G in NK cells and cytotoxic T lymphocytes (CTLs) in paired tumor tissues (group T, n = 44) and paracancerous tissues (group N, n = 44) from patients with PTC with the BRAF V600E mutation." (PMID 38341587, 2024). "For patients without the BRAF mutation, there is a progressive increase in thyroglobulin and calcitonin levels with the advancing tumor stage." (PMID 39767732, 2024). "As a consequence, these two BRAF-targeted agents achieved a considerable increased response rate, from 5% to 48%, with a single-agent administration (vemurafenib), with complete regression of the tumor registered in some patients." (PMID 38541077, 2024). "Patients had overall RAS/BRAF wild-type tumours in 35% and left-sided primary tumours in 70%." (PMID 37996507, 2024). "BRAF mutations in CRC are associated with more aggressive disease and poor outcome through associations with pathological features (poorly differentiated tumors, tumor budding), advanced disease stage at the time of diagnosis, and peritoneal metastasis." (PMID 38982444, 2024). "With ongoing research into integrating targeted therapies into first-line treatments, including HER2 and BRAF inhibitors, and the emerging utility of circulating tumor DNA for real-time molecular profiling, there has been a palpable shift towards more tailored therapeutic strategies." (PMID 38790167, 2024).